WNK4 (WNK lysine deficient protein kinase 4)
Diseases named in the same sentence as WNK4 in open-access papers (continued):
Sharing a sentence is not in itself a finding about the gene and the disease.
potassium deficiency (1 paper, 2025). A condition due to decreased dietary intake of potassium, as in starvation or failure to administer in intravenous solutions, or to gastrointestinal loss in diarrhea, chronic laxative abuse, vomiting, gastric suction, or bowel diversion. "Our analyses in KO mice demonstrated that during potassium deficiency, KS-WNK1 drives WNK body formation, amplifies NCC phosphoactivation, and increases WNK4-SPAK/OSR1 pathway expression." (PMID 40493421, 2025).
type 3 Bartter syndrome (1 paper, 2019). "Baseline normocalciuria following WNK4 deletion is a feature that resembles type 3 Bartter syndrome." (PMID 31496133, 2019).
cancer (2 papers, 2018 to 2023). A tumor composed of atypical neoplastic, often pleomorphic cells that invade other tissues. "Other genes within this cluster include CCDC170, WNK4 and AGR3 which have been reported to be implicated in these cancers." (PMID 30279965, 2018).
cardiovascular disorder (1 paper, 2016). A disease involving the cardiovascular system. "Second, in contrast to cases, the control subjects are relatively young but not age matched; however, more relative studies with larger population concerning other candidate gene polymorphisms or T/G polymorphism of WNK4 gene in relation to cardiovascular disorder are suggested." (PMID 27314050, 2016).
kidney disease (1 paper, 2019). "There are more studies of WNK4 in the kidney disease, but the study of WNK4 in the respiratory system is rarely reported." (PMID 30723408, 2019).
WNK4 also shares sentences with these, for which no sentence is quoted: Acidosis (2 papers); metabolic acidosis (2); age (1); autosomal dominant disease (1); coronary heart disease (1); dependent (1); depression (1); diabetic nephropathy (1); essential hypertensive (1); Gitelman syndrome (1); head and neck squamous cell carcinoma (1); hereditary disease (1); Hyperglycemia (1); Liddle syndrome (1); mesothelioma (1); mineralocorticoid excess (1); neurodegenerative disease (1); post-traumatic stress disorder (1); psoriasis (1); renal fibrosis (1); Stroke (1); tumor (1); type 2 diabetes mellitus (1).